BMP4 (bone morphogenetic protein 4)
Diseases named in the same sentence as BMP4 in open-access papers (continued):
Sharing a sentence is not in itself a finding about the gene and the disease.
testicular cancer (2 papers, 2023 to 2025). A primary or metastatic malignant neoplasm that affects the testis. "Levels of 38 transcripts in TCam-2 cells and 523 in NT2/D1 cells were altered by both activin A and BMP4 exposures, indicating the potential for cross-talk between activin A and BMP4 pathways in testicular cancer cells." (PMID 37048077, 2023). "With the ultimate goal of understanding how TGF-β superfamily ligands influence testicular cancer progression, this study examines activin A and BMP4 signalling in the seminoma-derived TCam-2 cell line and in the NT2/D1 cell line representing non-seminoma TGCTs." (PMID 37048077, 2023). "In summary, this study identified signalling pathways and novel signalling components that were altered in testicular cancer cell lines stimulated with activin A and BMP4, demonstrating the potential for antagonism and synergy between the two arms of TGF-β signalling in testicular cancer cells." (PMID 37048077, 2023). "These transcriptional changes, following short term exposures in testicular cancer cell lines, demonstrate how both activin A and BMP4 can influence multiple signalling pathways that modify cell migration, survival, and cell cycle progression behaviours in TGCTs." (PMID 37048077, 2023).
triple-negative breast carcinoma (2 papers, 2021 to 2023). An invasive breast carcinoma which is negative for expression of estrogen receptor (ER), progesterone receptor (PR), and human epidermal growth factor receptor 2 (HER2). "To avoid the limitation of the use of a single-cell line, we then examined the TGFβ effects on BMP4 and NOG expression in a panel of human triple-negative breast cancer cell lines (SUM159PT, SUM149PT, SUM229PE, SCP2)." (PMID 33649296, 2021).
ventricular septal defect (2 papers, 2019 to 2023). The presence of a defect (opening) in the septum that separates the two ventricles of the heart. "Conditional deletion of the BMP4 gene in cardiomyocyte in mice results in ventricular septal defects (VSD), atrioventricular canal defect (AVCD) and double outlet right ventricle (DORV)." (PMID 37627976, 2023).
virus infection (2 papers, 2013 to 2023). "Then, the expression of bmp4 upon virus infection was measured in the immune-related tissues including the gill, liver, spleen, kidney and intestine in zebrafish." (PMID 37833891, 2023). "In growth inhibition assays, which examine the viability of cells upon viral infection and expression of BMP-4, the U87s cultures exhibited similar growth inhibition after infection by GLV-1h285 or GLV-1h189." (PMID 23800258, 2013). "We demonstrated that Bmp4 plays a role in the host defense against virus infection." (PMID 37833891, 2023). "We further demonstrated that Bmp4 promotes the phosphorylation of Tbk1 and Irf3 through the p38 MAPK pathway, thereby inducing the production of type I IFNs in response to virus infection." (PMID 37833891, 2023).
vitamin D deficiency (2 papers, 2014 to 2022). A nutritional condition produced by a deficiency of VITAMIN D in the diet, insufficient production of vitamin D in the skin, inadequate absorption of vitamin D from the diet, or abnormal conversion of vitamin D to its bioactive metabolites. "Vitamin D deficiency in aging rats was also associated with decreased mRNA expression of bone morphogenetic protein 4 (Bmp4) and fibroblast growth factor-2 (Fgf-2), markers that play a role in satellite cell proliferation." (PMID 36364820, 2022). "Vitamin D deficiency in aged rats was also associated with decreased Bmp4 and Fgf2 mRNA expression." (PMID 36364820, 2022). "Here we speculate that vitamin D deficiency could result in a poor recruitment of SC into their proliferating state, due at least in part to a down-regulation of Fgf2, making them ready for programmed differentiation, as Bmp-4 is down-regulated." (PMID 25317198, 2014).
abortion (1 paper, 2023). the ending of pregnancy by removing a fetus or embryo before it can survive outside the uterus. "In G1, the uterine volume was associated with ERS1 upregulation (p = 0.0205), and abortion occurrence was related to BMP4 upregulation (p = 0.0342)." (PMID 36768749, 2023). "Several LM patients’ features and gene expressions were associated with AP exposure, but in women living in the MRSP, abortion occurrence was strongly associated with BMP4 upregulation." (PMID 36768749, 2023). "In the samples from women living in other cities of the metropolitan region, abortion occurrence was associated with BMP4 upregulation." (PMID 36768749, 2023).
acromegaly (1 paper, 2021). Acromegaly is an acquired disorder related to excessive production of growth hormone (GH) and characterized by progressive somatic disfigurement (mainly involving the face and extremities) and systemic manifestations. "In this context, we aimed to determine BMP-2 and BMP-4 levels in the gingival fluid to find any association with the health status of the periodontal tissue in those with acromegaly." (PMID 33421969, 2021). "In our present study, although the gingival BMP2 levels tend to be higher in those with healthier periodontal tissue, gingival BMP-2 and BMP-4 levels were similar in the active and inactive acromegaly patients." (PMID 33421969, 2021). "Gingival BMP-2 and BMP-4 levels were similar in the acromegaly and control groups." (PMID 33421969, 2021).
adenoma (1 paper, 2019). A neoplasm arising from the epithelium. "Similarly, blocking stromal BMP4 signals in epithelial cells leads to adenoma-like lesions and deletion of murine Smad4 in T cells results in GI cancer." (PMID 30783098, 2019).
alcoholic cirrhosis (1 paper, 2014). "We detected increased BMP4 and VEGF mRNA and protein in liver tissue from patients with alcoholic cirrhosis, suggesting that this pathway is associated with liver injury and may promote HCC-associated pathology by activating hepatocytes and endothelial cells." (PMID 23775568, 2014).
alcoholism (1 paper, 2024). "Sanger sequencing showed another heterozygous allelic variant c.751C > T in BMP4 in one of the 148 patients with secondary iron overload related to alcoholism." (PMID 39563390, 2024). "In addition, although the patient with the BMP4 p.H251Y variant was diagnosed as secondary iron overload in the clinical context, we speculate that the presence of this BMP4 variant may increase the risk of developing iron overload with the condition of alcoholism." (PMID 39563390, 2024).
alopecia (1 paper, 2021). Hair loss usually from the scalp. "Additionally, numerous signaling pathways, including the stimulatory pathways, such as the Wnt/β-catenin, STAT3, and Shh pathways, as well as the inhibitory pathways including Dkk-1, BMP4, and Dickkorpf-related protein are implicated in the treatment of alopecia." (PMID 34099599, 2021).
anaplastic gliomas (1 paper, 2013). "Patients with higher expression of BMP4 showed a significantly better prognosis in anaplastic gliomas and GBMs." (PMID 23590708, 2013).
ankylosis (1 paper, 2020). Fixation and immobility of a joint. "Exploring experimental SpA models would certainly supply more information on the impact of BMP-2/BMP-4 imbalance in this specific ankylosis." (PMID 33046134, 2020).
anodontia (1 paper, 2012). Anodontia is an extreme developmental dental anomaly characterized by the complete absence of all teeth. "Therefore, the presence of agnathia and anodontia observed in HhatCreface/Creface embryos correlates with the loss of Fgf8 and Bmp4 activity in the pharyngeal arch ectoderm." (PMID 23055936, 2012).
aplastic anemia (1 paper, 2024). Anemia resulting from bone marrow failure (aplastic or hypoplastic bone marrow). "After transfection of BMP4 gene into MSCs of patients with aplastic anemia (AA), the adipogenic differentiation ability is reduced, while the osteogenic differentiation is enhanced." (PMID 39015772, 2024).
brain cancer (1 paper, 2025). A primary or metastatic malignant neoplasm affecting the brain. "Other studies have genetically engineered MSCs to overexpress TNF-related apoptosis-inducing ligand (TRAIL) or bone morphogenetic protein 4 (BMP4), showing strong anti-tumor activity in brain cancer 6,7." (PMID 40083939, 2025).
brain glioma (1 paper, 2013). A malignant glioma that involves the brain. "Differential expression of BMP4 is closely related to the biological behavior of brain gliomas." (PMID 24099560, 2013). "Interestingly, we found that high BMP4 expression can increase bone metastasis from brain glioma." (PMID 24099560, 2013).
calcinosis (1 paper, 2024). Deposition of calcium in the tissues. "This may, in turn, accelerate the need of remodeling and renewal of endothelial cells, potentially leading to a shift towards a pro-osteogenic phenotype and underlines the potential role of BMP-4 in SSc calcinosis." (PMID 39697336, 2024).
cardiac arrest (1 paper, 2023). Cessation of breathing and/or cardiac function. "Clinically, circulating BMP4 elevation is detected in patients with cardiac arrest, and is relevant to the decreased survival and unfavorable neurological outcome." (PMID 36518009, 2023).
carotid atherosclerosis (1 paper, 2022). A thickening and loss of elasticity of the walls of carotid arteries that occur with formation of atherosclerotic plaques. "For instance, elevated serum BMP4 levels have been correlated with carotid atherosclerosis in T2D patients." (PMID 35614516, 2022).
Carpenter syndrome (1 paper, 2018). An extremely rare autosomal recessive syndrome characterized by premature closure of cranial sutures leading to cone-shaped head, fusion of the digits, and the presence of more digits than normal. "Mutations of the gene MEGF8 cause Carpenter syndrome in humans, and the mouse orthologue has been functionally associated with Nodal and Bmp4 signalling." (PMID 29884872, 2018).
cerebral small vessel disease (1 paper, 2021). Cerebral small vessel disease is the term currently used to pathological processes that affect the brain parenchymal circulation (arterioles, capillaries, and veins). "In addition to PDGFR-β, a proportion of pericytes also express the bone morphogenetic protein-4 (BMP4) that can be altered in cerebral small vessel disease." (PMID 34340718, 2021).
cerebrovascular disease (1 paper, 2024). "The genes related to cardiovascular and cerebrovascular disease annotated by the Hippo signaling pathway were Bmp4, Tcf7l2, and Wnt16." (PMID 38195688, 2024).
cholesteatoma (1 paper, 2023). A pathologic process characterized by the proliferation of keratinizing squamous epithelium resulting in the accumulation of keratin and cells in the middle ear and/or mastoid.
chordoma (1 paper, 2016). Chordomas are rare malignant tumors arising from embryonic remnants of the notochord in axial skeleton. "In skull-based chordomas, the BMP-4/SMAD signaling pathway upregulation was reported to be the dominant molecular mechanism of chordoma pathogenesis, which indicated poor clinical outcome." (PMID 27661009, 2016).
chorioamnionitis (1 paper, 2012). A morphologic finding indicating inflammation of the fetal sac membranes. "Shh and BMP4 expression decreased in response to LPS-induced chorioamnionitis indicating increased differentiation of thymic T-cells." (PMID 22693607, 2012).
chronic heart failure (1 paper, 2020). "In this paper, we have presented the impact of relatively long‐lasting spontaneous physical activity on the BMP4 content in the heart and bone of the healthy mice and the mice with chronic heart failure." (PMID 32319199, 2020). "The aim of this study was to evaluate the effect of spontaneous physical activity on the expression of BMP4 in the heart and tibia of the transgenic (Tgαq*44) mice, representing a model of chronic heart failure." (PMID 32319199, 2020).
Cognitive impairment (1 paper, 2026). Abnormal cognition is characterized by deficits in thinking, reasoning, or remembering. "For example, BMP4 overexpression in transgenic mice impairs memory and increases Aβ and tau accumulation, whereas lower levels of BMP6 in AD patients are associated with cognitive impairment." (PMID 41480410, 2026).
colorectal adenoma (1 paper, 2011). An adenoma that arises from the colon or rectum. "Although in part speculative the demonstration that colorectal adenomas segregated with the p.C373S mutation in the one family and the fact that the case harboring p.W325C had a first-degree relative affected with CRC suggests that BMP4 mutations are likely to confer a moderate-high risk of CRC." (PMID 20949628, 2011).
colorectal polyps (1 paper, 2014). "In order to provide a rapid and stable model of colorectal polyps, we constructed an F1 mouse colorectal polyp model using transplacental RNAi technology to silence the BMP4 gene." (PMID 24806485, 2014). "In conclusion, silencing of the BMP4 gene using transplacental RNAi injection can induce formation of colorectal polyps in mice." (PMID 24806485, 2014). "The distribution of colorectal polyps in mice was consistent with the polyp distribution observed in the clinic, and the mRNA level of the BMP4 gene was significantly reduced in the rectum compared to the colon, which might explain why rectal polyps are more common in the clinic." (PMID 24806485, 2014).
cryptorchidism (1 paper, 2021). The failure of one or both testes of a male fetus to descend from the abdomen into the scrotum during the late part of pregnancy. "For example, the positively selected gene Bone Morphogenetic Protein 4 (BMP4) encodes a protein involved in multiple human cancers, especially cancer in male external genitalia, and cryptorchidism." (PMID 34702182, 2021).
dementia (1 paper, 2024). Loss of intellectual abilities interfering with an individual's social and occupational functions. "Our findings included well-known dementia-associated protein biomarkers, such as BMP4, CD200, MANF, PLXNB1, PLXNB3, and SMPD1 for AD and BCAN, NCAN, and THY1 for VD, as well as uncovering novel proteins associated with AD or VD." (PMID 39226887, 2024).
demyelinating disease (1 paper, 2016). A broad group of disorders that affect the myelin sheaths that cover the neurons. "BMP4 was first implicated in demyelinating disease through mRNA upregulation in demyelinated Multiple Sclerosis (MS) brain lesions." (PMID 27293450, 2016). "Given the well-characterised inhibitory effect of BMP4 on oligodendrocyte production, it has been extensively studied in the context of demyelinating disease." (PMID 27293450, 2016).
developmental delay (1 paper, 2013). "Normal notch1B and tie2 expression suggest that the failure of bmp4 and versican to become AV canal-restricted was not merely due to developmental delay, nor to an overall mispatterning of AV boundaries." (PMID 24311987, 2013).
diabetic cardiomyopathy (1 paper, 2023). Diabetic cardiomyopathy is a disorder of the heart muscle in people with diabetes. "BMPs (BMP2, BMP4, and BMP7) elicit anti-atherogenic and anti-inflammatory effects, while reducing LV remodeling and preserving cardiac function in diabetic cardiomyopathy." (PMID 37240345, 2023).
diabetic retinopathy (1 paper, 2023). "The goal of this study was to test whether BMP4 contributes to the pathogenesis of diabetic retinopathy (DR)." (PMID 37174679, 2023). "However, the association between BMP4 signaling and endothelial cell dysfunction in diabetic retinopathy has not yet been elucidated." (PMID 37174679, 2023).
dialysis (1 paper, 2018). "Furthermore, peritoneal tissue from peritoneal dialysis patients showed less prominent immunostaining than control tissue for IGFBP4 and BMP4 on the peritoneal surface." (PMID 29774544, 2018).
diffuse intrinsic pontine glioma (1 paper, 2022). A neuroglial tumor that arises from the middle portion of the brain stem. "The authors also showed that the BMP4 treatment of diffuse intrinsic pontine glioma (DIPG) cells induced a stemness blockade accompanied by decreased SOX2 and OLIG2 expression, further validating our findings." (PMID 36497175, 2022).
endometrial cancer (1 paper, 2017). Primary or metastatic malignant neoplasm involving the endometrium (mucous membrane that lines the endometrial cavity). "The Hand1 protein has been isolated in endometrial cancer samples and has been expressed preferentially in mESCs cultured with BMP4, allowing for trophoblast differentiation from mESCs, a common pathway with humans." (PMID 28716123, 2017).
endometriosis (1 paper, 2024). The growth of functional endometrial tissue in anatomic sites outside the uterine body. "We focused on the roles of BMP/SMAD1/5 signaling given that we observed altered expression of BMP ligands (BMP4, BMP6) as well as decreased expression of canonical SMAD1/SMAD5 targets in the decidualizing stromal cells from individuals with endometriosis." (PMID 38402336, 2024).
enthesitis (1 paper, 2016). Inflammation at the site of insertion of ligaments, tendons, and other fibrous structures into bone. "Expressions of further BMP family members (BMP-2, BMP-4, and BMP-7) were reportedly increased at sites of enthesitis in a mouse model of SpA and at the Achilles tendon in biopsies of early-stage humans enthesopathy." (PMID 27314037, 2016).
esophagitis (1 paper, 2022). An acute or chronic inflammatory disease affecting the esophageal wall. "We also demonstrated that the BMP4/pSMAD pathway is upregulated in the surgical rat esophagitis-IM model 20–22 weeks post esophago-jejunostomy and that BMP4 overexpression together with CDX2 induces upregulation of intestinal type of genes in a surgical mouse esophagitis-IM model." (PMID 34718471, 2022). "Our studies showed that BMP4 is upregulated in esophagitis and (intestinal) metaplasia." (PMID 34718471, 2022).
fracture (1 paper, 2021). "Although several BMPs, for example BMP-2 and BMP-4, possess excellent osteogenic properties, their levels remain very low in the peripheral blood after a bone fracture." (PMID 33833129, 2021).
germ cell tumours (1 paper, 2023). "However, because there is an imperative to understand how germ cell tumours are affected by extrinsic factors, we also used Ingenuity Pathway software to explore the potential for upstream regulators to influence the outcomes of activin A and BMP4 signalling in these cells." (PMID 37048077, 2023).
haemochromatosis (1 paper, 2023). "In our study, application of GREEN-DB led to identification of candidate variants in several cases including a deep intronic variant in BMP4 in a patient with Kapur-Toriello syndrome and variants in HSD3B7 and BMP6 in a patient with neonatal haemochromatosis." (PMID 37946251, 2023).
hematoma (1 paper, 2022). A hematoma is a collection of blood from a vascular structure into an extravascular space. "In line with this, the expression of osteogenic differentiation markers RUNX2, ALP, BMP4, and Noggin as well as the chondrogenic differentiation marker SOX9 were all significantly lower in smokers’ hematomas (comp." (PMID 35621464, 2022).